TXNDC15 (thioredoxin domain containing 15)
Description:
Acts as a positive regulator of ciliary hedgehog signaling (By similarity). Involved in ciliogenesis.
Synonyms: C5orf14; TMX5; FLJ22625; 2310047H23Rik; BUG; MKS14; UNQ335
Tractability: Antibody: UniProt predicts a signal peptide or a membrane-spanning region; its Gene Ontology location is reachable by antibodies, with medium confidence. PROTAC: ubiquitination databases record sites on it; its protein half-life has been measured.
Gene: Protein-coding gene on chromosome 5 (134,874,318 to 134,901,635, forward strand). Ensembl gene ENSG00000113621.
Subcellular location: Cell projection, cilium membrane
Subcellular location (Human Protein Atlas): Golgi apparatus
Gene Ontology:
Molecular function: protein binding
Biological process: cilium assembly; positive regulation of smoothened signaling pathway
Cellular component: cilium; ciliary membrane
Genetic constraint (gnomAD): Loss-of-function variants: 24 observed, 34.61 expected, observed/expected ratio (o/e) 0.69, 90% interval 0.5 to 0.98. The upper end of that interval is the gene's LOEUF score, 0.98, which puts it in group 4 of 6, group 1 being the genes least tolerant of losing a copy. Missense variants: 385 observed, 466.23 expected, observed/expected ratio (o/e) 0.83, 90% interval 0.76 to 0.9. Synonymous variants: 169 observed, 178.85 expected, observed/expected ratio (o/e) 0.94, 90% interval 0.83 to 1.07.
Gene-disease validity (ClinGen):
ClinGen rates the evidence that TXNDC15 causes each of these diseases.
ciliopathy (autosomal recessive): Strong. A genetic disorder of the cellular cilia or the cilia anchoring structures, the basal bodies, or of ciliary function.
Homologues: Orthologues: chimpanzee TXNDC15 (99% identical), macaque TXNDC15 (91% identical), pig TXNDC15 (85% identical), dog TXNDC15 (84% identical), rabbit TXNDC15 (80% identical), guinea pig TXNDC15 (79% identical), mouse Txndc15 (77% identical), rat Txndc15 (74% identical), tropical clawed frog txndc15 (51% identical), zebrafish txndc15 (41% identical), Caenorhabditis elegans C53D6.4 (19% identical), Drosophila melanogaster bug (16% identical).
Diseases named in the same sentence as TXNDC15 in open-access papers:
TXNDC15 is named in the same sentence as 19 diseases in open-access papers, as found by Europe PMC text mining. Sharing a sentence is not in itself a finding about the gene and the disease. The quoted sentences say what the papers report.
ciliopathy (3 papers, 2016 to 2023). "Of the remaining 40 families, nine (22.5%) had variants in eight novel candidate ciliopathy genes (TXNDC15, TRAPPC3, EXOC3L2, FAM98C, C17orf61, LRRCC1, NEK4, and CELSR2)." (PMID 27894351, 2016).
Meckel syndrome (3 papers, 2016 to 2024). "Taken together, our data support a causal role for the biallelic truncating mutations we identified in TXNDC15 and the Meckel-Gruber syndrome phenotype in these patients." (PMID 27894351, 2016).
meckel syndrome 14 (1 paper, 2024). "Biallelic variants of TXNDC15 gene (OMIM: * 617778) which encodes a thioredoxin‐domain containing transmembrane protein are the cause of Meckel syndrome 14 (MKS14, OMIM: # 619879)." (PMID 38073519, 2024).
occipital encephalocele (1 paper, 2019). "Here, we report the same prenatal findings: bilateral postaxial polydactyly, occipital encephalocele, and bilateral polycystic kidneys caused by compound heterozygous variants in the TXNDC15 gene." (PMID 30851085, 2019).
TXNDC15 also shares sentences with these, for which no sentence is quoted: cancer (8 papers); tumor (4); gastric cancer (2); prion disease (2); bladder cancer (1); breast cancer (1); colitis (1); esophageal cancer (1); ileitis (1); Immunodeficiency (1); infection (1); non-small cell lung carcinoma (1); Parkinson disease (1); polycystic kidneys (1); ZIKV infection (1).